BAG2 (BAG cochaperone 2)
Diseases named in the same sentence as BAG2 in open-access papers (continued):
Sharing a sentence is not in itself a finding about the gene and the disease.
cervical cancer (continued). "This suggests that STING‐mediated degradation of HPV E7 is only a part of the BAG2‐STING axis effect on cervical cancer development, and that BAG2 regulation of HPV E7 proteins may be through a cumulative effect of stabilizing STING protein level." (PMID 40364789, 2025). "Thus, we demonstrated that BAG2 inhibits the proliferation and migration of cervical cancer cells by regulating STING, and this effect is present in both HPV‐positive and HPV‐negative tumor cells." (PMID 40364789, 2025). "In addition, we found that mRNA and protein levels of BAG2 were significantly reduced in cervical cancer tissues compared with paracancerous tissues." (PMID 40364789, 2025). "Notably, clinical cervical cancer samples revealed a positive correlation between BAG2 and STING levels, with low BAG2 expression is strongly linked to advanced disease and poor prognosis in cervical cancer." (PMID 40364789, 2025). "In addition, it is worth noting that methylation levels in the BAG2 promoter region were significantly elevated in cervical cancer tissues, suggesting a potential epigenetic regulation of BAG2 during cervical cancer progression." (PMID 40364789, 2025). "In conclusion, the data strongly suggest a correlation between BAG2 and cervical cancer progression and prognosis, highlighting that diminished BAG2 expression may contribute to the malignant progression and poor prognosis of the disease." (PMID 40364789, 2025). "Moreover, BAG2 controls cervical cancer cell proliferation and migration and inhibits cancer progression by modulating STING‐mediated type I interferon signaling." (PMID 40364789, 2025). "It is suggested that BAG2 may have a broader immunomodulatory function in cervical cancer." (PMID 40364789, 2025). "Given the significance of BAG2 in the regulation of STING, we decided to investigate the relationship between BAG2 and major clinical characteristics of cervical cancer." (PMID 40364789, 2025). "We also clarify that BAG2 stabilizes STING by preventing STING from being ubiquitinated by STUB1, thereby preventing cervical cancer proliferation and metastasis." (PMID 40364789, 2025). "Based on IP‐MS analysis, BAG2 is confirmed to be essential for ubiquitination and protein homeostasis regulation of STING in cervical cancer." (PMID 40364789, 2025). "In summary, the BAG2‐STING axis exerted significant tumor suppressor effects in both HPV‐positive and HPV‐negative cervical cancer cells." (PMID 40364789, 2025). "The BAG2‐STING axis plays a pivotal role in the development of cervical cancer, and targeting BAG2 may be a potential therapeutic strategy for cervical cancer." (PMID 40364789, 2025). "Moreover, we demonstrated a significant positive correlation between BAG2 and STING protein levels by analyzing cervical cancer clinical samples." (PMID 40364789, 2025). "BAG2 inhibits the ubiquitination and degradation of STING by forming a complex with STUB1, thereby activating the type I IFN signaling pathway and inhibiting the development of cervical cancer." (PMID 40364789, 2025). "Notably, the protein levels of BAG2 and STING were quantitatively assessed by IHC in cervical cancer tissue samples from the Zhongnan Hospital cohort, and a strong positive correlation was found between the protein levels of BAG2 and STING in cervical cancer tissues." (PMID 40364789, 2025). "Overexpression of BAG2 in murine‐derived cervical cancer U14 cell line and obtaining the same results when stimulated with HT‐DNA and cGAMP, suggesting that the function of BAG2 in regulating type I interferon responses is not species‐specific." (PMID 40364789, 2025). "Notably, BAG2 expression was significantly reduced in cervical cancer, while no significant changes were observed in other BAG family members (BAG1, BAG3, BAG4, BAG5, and BAG6), suggesting a unique role for BAG2 in cervical cancer." (PMID 40364789, 2025).
lung carcinoma (3 papers, 2015 to 2020). "Overexpression of BAG2 has been associated with poor disease‐specific survival in lung cancer, whereas the SULT1E1 polymorphism rs4149525 has been associated with shortened overall survival in NSCLC." (PMID 34766125, 2020).
lymph node metastasis (3 papers, 2021 to 2024). "The high-confidence driver genes RHPN2, MUC16, and MUC4 were significantly mutated in both small- and large-sized rNEN specimens, whereas mutations in MAN2A1, and BAG2 were only identified in large-sized specimens diagnosed with lymph node metastases." (PMID 39548061, 2024).
ovarian carcinoma (3 papers, 2020 to 2023). A malignant neoplasm originating from the surface ovarian epithelium. "Moreover, a recent study reported that the level of BAG2 protein is increased in fibroblasts that are co-cultured with ovarian cancer and inferred that BAG2 expression in CAF could be associated with tumor progression through multiple cellular processes." (PMID 34572878, 2021). "High-throughput sequencing or proteomics of different types of tumors reflects the high expression of BAG2 in cancer, including ovarian cancer, papillary thyroid carcinoma, fibrosarcoma and multiple myeloma." (PMID 32082999, 2020). "A recent study showed that BAG2 expression is elevated in fibroblasts co-cultured with ovarian cancer cells, indicating that BAG2 could be elevated in CAFs and playing a role in stress response and cellular senescence pathways." (PMID 34572878, 2021).
endometriosis (2 papers, 2020 to 2025). The growth of functional endometrial tissue in anatomic sites outside the uterine body. "CHIP degraded ERβ instead of ERα via the ubiquitin-proteasome pathway, while BAG2 impaired the CHIP-mediated degradation of ERβ in cultured HESCs derived from human endometriosis." (PMID 33987175, 2020). "To test this hypothesis, we measured the expression of BAG2 in human and mouse endometriosis/normal tissues and in the HESCs." (PMID 33987175, 2020). "Using a human endometrial organoid chip model, a consistent downregulation of ERα alongside upregulation of ERβ, BAG2, and MDM2 in both human endometriosis specimens and mouse models was observed in the study." (PMID 41156372, 2025). "To evaluate the effects of BAG2 and MDM2 in vivo, we established a mouse model of endometriosis and detected." (PMID 33987175, 2020). "The expression of ERα was downregulated while that of ERβ, BAG2, and MDM2 was upregulated in human endometriosis and in the mouse model." (PMID 33987175, 2020). "Our findings suggest that the interference of BAG2 and MDM2 may have therapeutic effects in endometriosis." (PMID 33987175, 2020). "Although there is no published evidence about the relationship between endometriosis and BAG2, it is known that BAG2 can regulate ubiquitination of target proteins mediated by hsc70-interacting protein (CHIP)." (PMID 33987175, 2020). "Besides, we found that BAG2 and MDM2 were both elevated in the endometriosis tissues compared with normal endometrium." (PMID 33987175, 2020). "Knockdown of both BAG2 and MDM2 alleviated the development of endometriosis in mice." (PMID 33987175, 2020). "Furthermore, it also validated that CHIP and MDM2 mediate the degradation of ERβ and ERα, respectively, via the ubiquitin–proteasome pathway, and that targeted interference with BAG2 and MDM2 may elicit therapeutic effects in endometriosis." (PMID 41156372, 2025).
lung adenocarcinoma (2 papers, 2010 to 2025). A carcinoma that arises from the lung and is characterized by the presence of malignant glandular epithelial cells. "BAG-1, BAG-2, BAG-5 might be the potential protective factors while BAG-4 is possible risk factor of lung adenocarcinoma." (PMID 20959066, 2010).
oral squamous cell carcinoma (2 papers, 2021 to 2023). "BAG2 has been found to be overexpressed in oral squamous cell carcinoma and is associated with a poor prognosis." (PMID 34885041, 2021). "BAG2 is related to poor prognosis and promotes the proliferation, invasion, and migration of oral squamous cell carcinoma cells by activating the MAPK signaling pathway." (PMID 36593950, 2023).
breast tumor (1 paper, 2022). "We therefore next examined the co-expression correlation between HSPs and co-chaperones including HSP90 family (HSP90AA1, HSP90AB1), HSP70 family (HSPA1A, HSPA1B, HSPA8) and BAG family (BAG1, BAG2, BAG3) among 960 breast tumor samples registered in the Cancer Genome Atlas (TCGA)." (PMID 36114410, 2022).
cognitive deficits (1 paper, 2018). "Curiously, another non-selective agonist of CB1R, curcumin (an antioxidant polyphenol) prevented cognitive deficits when administered for 30 consecutive days after icv-STZ injection and when tested in vitro curcumin up-regulated BAG2 levels and reduced p-tau levels." (PMID 30333717, 2018).
dilated cardiomyopathy (1 paper, 2023). Cardiomyopathy which is characterized by dilation and contractile dysfunction of the left and right ventricles. "These included pathways such as actin cytoskeleton signaling, BAG2 signaling, calcium signaling, dilated cardiomyopathy signaling, gluconeogenesis, glycolysis, ILK signaling, integrin signaling, oxidative phosphorylation, RhoGDI signaling, and signaling by Rho Family GTPases." (PMID 37658118, 2023).
metastatic tumors (1 paper, 2015).
microcephaly (1 paper, 2026). A congenital or acquired developmental disorder in which the circumference of the head is smaller than normal for the person's age and sex. "Notably, microcephaly-associated WDR62 mutations disrupt interaction with BAG2 and fail to restore HPRT levels." (PMID 41787126, 2026).
neuroblastoma (1 paper, 2022). Neuroblastoma (NB) is the most common solid, extracranial childhood tumor. "Coherently, the chimeric RNA zinc finger protein 451 (ZNF451)-BAG cochaperone 2 (BAG2) fusion, highly expressed in neuroblastoma, generated a novel oncogenic protein with distinct protein–protein binding properties compared to wild-type BAG2." (PMID 35269953, 2022).
Pancreatic Cancer (1 paper, 2022). "The top five pathways according to p value were SPINK1 Pancreatic Cancer Pathway, BAG2 Signaling Pathway (p = 9.20E−8), Aryl Hydrocarbon Receptor Signaling (p = 4.22E−7), Clathrin-mediated Endocytosis Signaling (p = 7.81E−7), and Protein Ubiquitination Pathway (p = 8.22E−7)." (PMID 35780404, 2022).
prostate carcinoma (1 paper, 2023). A carcinoma that arises from epithelial cells of the prostate gland. "Furthermore, oxidative phosphorylation, p70S6K, unfolded response, TREM1, NFκB, ERK5, IL8, BAG2, Integrin, and VEGF signaling were identified (z score 5.574 to −4.811) as top canonical pathways for ARLow/mCRPC/NEPC prostate cancer." (PMID 37476073, 2023).
thyroid carcinoma (1 paper, 2016). "BAG2 exhibits pro-apoptotic properties and is demonstrated to be up-regulated in proteasome inhibitor-induced apoptosis in thyroid carcinoma cell." (PMID 26955879, 2016).
triple-negative breast carcinoma (1 paper, 2020). An invasive breast carcinoma which is negative for expression of estrogen receptor (ER), progesterone receptor (PR), and human epidermal growth factor receptor 2 (HER2). "BAG2 was also highly expressed in triple negative breast cancer and associated with cancer metastasis." (PMID 32082999, 2020).
cancer (21 papers, 2010 to 2025). A tumor composed of atypical neoplastic, often pleomorphic cells that invade other tissues. "Increasing evidence has implicated BAG2 in the pathogenesis of various diseases, including cancers and neurodegenerative diseases." (PMID 34572878, 2021). "Bcl2-associated athanogene 2 (BAG2) is a multifunctional co-chaperone that participates in the progression of cancers and some other degenerative diseases." (PMID 33987175, 2020). "Overexpression of BAG2 is significantly associated with poor prognosis in different types of cancer." (PMID 26271008, 2015). "BCL2-associated athanogene 2 (BAG2) plays a crucial role in cellular senescence in cancer cells by c-Myc-mediated regulation." (PMID 24312579, 2013). "In addition, patients with poor cancer status (with tumor, p < 0.05) or with vascular invasion (p < 0.05) was associated with higher expression of BAG2." (PMID 34257542, 2021). "We further investigated whether BAG2 overexpression is associated with poor prognosis in cancer patients by using the PrognoScan database." (PMID 26271008, 2015). "The previous study showed that BAG2 could be elevated in cancer associated fibroblasts (CAFs)." (PMID 34572878, 2021). "Further study is warranted to elucidate the role of BAG2 in the interaction between the cancer cells and the tumor stroma, which contributes to metastasis." (PMID 34572878, 2021). "As a member of the BAG family, BAG2 is also found to play an essential role in several types of cancer." (PMID 34257542, 2021). "Statistical results revealed that the BAG2 was low expressed in 96.3% (182/189) of normal gastric mucosa and high expressed in 48.1% (91/189) of cancer tissue (P < 0.01)." (PMID 32082999, 2020). "In this review, we summarize the currently known functions of BAG2 in cancer and neurodegenerative disorders." (PMID 28536620, 2016). "An increasing number of studies have indicated that BAG2 is involved in the pathogenesis of various diseases, including cancers and neurodegenerative diseases." (PMID 28536620, 2016). "The amplification of BAG2 was observed in many types of human tumors as analyzed by employing the cBioportal for Cancer Genomics, suggesting that gene amplification is an important mechanism for BAG2 overexpression in tumors." (PMID 26271008, 2015). "LOXL1 could also stabilize the molecular chaperone regulator BAG2 and impede the apoptosis of cancer cells." (PMID 38267662, 2024). "Several previous studies about BAG2 have indicated a significant role in cancer progression." (PMID 36593950, 2023). "In addition, compared with poorly differentiated carcinoma, in well-differentiated and moderately differentiated carcinoma, the high expression of BAG2 showed a significantly poor prognosis." (PMID 32082999, 2020). "Most previous studies on BAG2 emphasized its important role in cancer cell metastasis." (PMID 28536620, 2016). "Importantly, analysis of several database from Oncomine showed that BAG2 is frequently overexpressed in many types of cancer." (PMID 26271008, 2015). "Interestingly, BAG2 functions as an oncogene in multiple cancer types." (PMID 34831344, 2021).
cancer (continued). "Notable examples—such as ANO1, BAG2, DHCR7, MMP2, and TRAM2 —align with prior studies linking these genes related to cancer proliferation or metastasis in multiple cancer types." (PMID 40361356, 2025). "In summary, in the present work, we report that BAG2, MAD2L1, and MDK are bona fide cancer-driver genes for MPM worth of further studies." (PMID 39300217, 2024). "The co-chaperone BAG2 modulates the activity of HSP70/HSC70 by promoting substrate release; most previous studies on BAG2 emphasize its important role in cancer cell metastasis." (PMID 29534015, 2018). "By impeding the interaction of BAG2 with CHIP, it was found that the normal apoptotic pathway was restored and that this interaction may trigger multiple cellular effects in cancer cells by affecting nucleosome assembly." (PMID 40755756, 2025).